EPO (erythropoietin)
Diseases named in the same sentence as EPO in open-access papers (continued):
Sharing a sentence is not in itself a finding about the gene and the disease.
anemia (continued). "For recombinant erythropoietin, which is used for the therapy of anemia, the presence of an alternative EphB4 receptor in tumor cells has been shown." (PMID 37894821, 2023). "The child was given iron succinate and erythropoietin to improve anemia after a routine blood examination after admission." (PMID 37596520, 2023). "This single centered retrospective study included patients presented with isolated anemia and had their EPO levels measured at their first visit." (PMID 37741889, 2023). "In the setting of hyperchloremia, kidney perfusion can be affected by renal vasoconstriction, which leads to acute kidney injury (AKI) and suppression of erythropoietin, resulting in anemia." (PMID 37520482, 2023). "Development of anaemia after EPT birth has so far mainly been attributed to the decreasing erythropoietin levels following birth." (PMID 37169579, 2023). "Thus, EPO deficiency may contribute to anemia in patients with cancer." (PMID 37208766, 2023). "The use of other treatment options, like EPO therapy and iron supplementation for the treatment of anemia in COPD patients, requires more promising literature reviews." (PMID 37065412, 2023). "(iii) Further studies are necessary for assessing the correlation of medications (such as erythropoietin stimulating agents, calcium, and vit-D supplementation) with anemia status in ESRD patients." (PMID 36815007, 2023). "Accordingly, the FDA has approved the use of EPO (1993) and darbepoetin (2002) in patients with chemotherapy-induced anemia." (PMID 38029231, 2023). "The main trigger for EPO formation is a decrease in arterial oxygen content due to anemia or hypoxia, which usually results in an exponential increase in EPO production." (PMID 37065412, 2023). "The reduction in erythropoietin (EPO) production is one of the main reasons for anemia in ESRD patients." (PMID 36815007, 2023). "Effective methods to preoperative correction of anemia include the use of erythropoietin (EPO) and oral or intravenous (IV) iron supplementation." (PMID 36631873, 2023). "Taken together, our data for the first time provides in vivo evidence that ineffective erythropoiesis in MDS mice is responsive to iron chelation with DFP, normalizing erythroblast iron trafficking and restoring EPO responsiveness to reverse anemia in MDS." (PMID 38153418, 2023). "The documented causes of anemia in CKD patients are multifactorial and include deficiency of erythropoietin, resistance to erythropoietin, reduced red blood cell lifespan, iron deficiency, chronic inflammatory process, and uremic milieu." (PMID 36730249, 2023). "Recombinant human erythropoietin (rHuEPO) is one of the most effective drugs for the treatment of anemia in patients with chronic kidney disease." (PMID 36839666, 2023). "Intradialytic muscular cramps, asthenia, hypotension, decreased oxygen consumption, cardiomyopathy, decreased ejection fraction, myopathy or muscle weakness, and anemia needing high doses of EPO are a few of these symptoms." (PMID 36836532, 2023). "Since anemia can be attributed to concurrent kidney dysfunction due to declined erythropoietin production, we searched for correlations between kidney function, red blood cell parameters, and iron-related variables." (PMID 37623041, 2023). "Traditionally, erythropoietin-stimulating agents (ESAs) and iron supplementation have been used to manage anaemia in cases of CKD." (PMID 37623232, 2023). "The presence of CKD, with its potential to reduce erythropoietin production, plays a significant role in the pathogenesis of anemia in many cases of HF, exacerbating the overall health burden." (PMID 38137939, 2023). "The functional features of the interaction of erythroid and tumor cells lead to the need for new approaches in the use of erythropoietin for the treatment of anemia and the reasons for the ineffectiveness of antiangiogenic drugs." (PMID 37894821, 2023).
anemia (continued). "On the other hand, hypermethylation of the erythropoietin promoter and enhancer in myofibroblasts has also been shown to lead to decreased erythropoietin production and anemia in CKD." (PMID 37893201, 2023). "If anemia is present, erythropoietin increases, to activate hematopoiesis, which, in turn, increases sTfR levels." (PMID 39196095, 2023). "Iron-deficiency anemia, a common type of anemia in patients with CKD, is caused by iron and erythropoietin deficiencies and a erythropoietin hypo-responsiveness, which reduces the lifespan of RBCs and enhances the risk of oxidative stress." (PMID 36674173, 2023). "At the same time, anemia stimulates the kidney to produce erythropoietin (EPO), which can stimulate erythropoiesis, thus improving the anemia status." (PMID 37746281, 2023). "Previous studies indicated that the levels of serum EPO increased in β−thalassemia patients to compensate for anemia." (PMID 38328786, 2023). "In the present study, more than half (56.1%) of the participants received EPO to manage anemia related to CKD." (PMID 38029231, 2023). "Subsequently, to compare and evaluate the relationship of serum EPO, sFas levels with anemia, and outcomes in patients with NDD-CKD over a long follow-up period." (PMID 37390095, 2023). "The erythropoietin suppression by amphotericin B has been proposed to contribute to the development of anemia." (PMID 37864131, 2023). "Erythropoiesis-stimulating agents (ESAs) are first-line therapy to treat anemia in patients with LR-MDS with serum erythropoietin (EPO) levels ≤500 U/l and low transfusion burden." (PMID 37752285, 2023). "Anemia in CKD is associated with various factors, such as inadequate production of erythropoietin and the availability of iron and its binding protein." (PMID 36855344, 2023). "Anemia is common among dialysis patients, and patients frequently need erythropoietin to maintain hemoglobin levels within the target." (PMID 36655149, 2023). "Excessive urinary losses of iron, TF, EPO, transcobalamin, and/or copper in relation to anemia and its ineffectiveness after iron and EPO supplementation in nephrotic syndrome were extensively reviewed." (PMID 36855344, 2023). "Secondly, we emulated the conditions seen in CKD patients by surgically removing 5/6 of the rat’s kidney, resulting in prolonged anemia due to impaired EPO production." (PMID 37960326, 2023). "We emphasize the need for adequate dosing of RBV to treat hepatitis E infection and we recommend immediate or very early substitution of EPO in the case of anemia or a drop in hemoglobin." (PMID 37375540, 2023). "Patients with advanced chronic kidney disease (CKD) develop anemia, in part due to insufficient endogenous erythropoietin (EPO) production related to the progression of CKD1." (PMID 38123661, 2023). "Upregulation of EPO in malaria-related anaemia is essential for effective bone marrow compensatory response to correct the anaemia." (PMID 36989322, 2023). "The etiology of anemia in CKD is multifactorial but mainly occurs due to inadequate production of erythropoietin (EPO)." (PMID 37390095, 2023). "Ultimately all of these mechanisms lead to anemia of chronic disease, a common condition in cachexia Currently, erythropoiesis-stimulating-agents such as epopoetin alpha, which has similar actions as endogenous erythropoietin, are given to treat this anemia." (PMID 38022578, 2023). "Sixteen patients (88.9%) were on ESA for the treatment of anemia, and eight patients each were on erythropoietin (EPO) and darbepoetin alfa." (PMID 37089609, 2023). "Treatment with erythropoietin, adjuvant recombinant human erythropoietin (rHuEPO) has been documented as having good compliance in combatting anaemia, although further studies are needed to validate its efficacy and safety." (PMID 37686128, 2023).
anemia (continued). "The mechanisms of platinum‐induced anaemia involve direct suppression of erythroid progenitor cells within the bone marrow and nephrotoxic effects on erythropoietin‐producing cells within the kidney." (PMID 35837812, 2023). "Chronic inflammation and inflammatory cytokine production contributed to decreased EPO stimulated erythropoiesis resulting in anemia of chronic disease." (PMID 36895793, 2023). "EPO has been used to treat anemia related to chronic kidney disease (CKD), cancer chemotherapies, zidovudine patients with HIV infection, etc.." (PMID 37631301, 2023). "Transfusions partially correct the anemia, acutely and chronically decreasing erythropoietin secretion." (PMID 35905974, 2023). "Inflammatory cytokines can result in anemia by decreased production of endogenous EPO, delayed response of erythroid progenitor to EPO, and increased production of hepcidin which was extensively reviewed." (PMID 36855344, 2023). "Erythropoietin, to compensate for anemia, can inhibit eryptosis, but high levels of erythropoietin promote the formation of red blood cells with a relatively high sensitivity to eryptosis triggers." (PMID 37894821, 2023). "Recombinant human erythropoietin (rHuEPO) was an erythropoiesis stimulating agent (ESA) introduced into clinical practice to treat anemia related to CKD in the 1990s and successfully improved clinical outcomes and quality of life of patients with CKD1." (PMID 38123661, 2023). "Neutralizing antibodies of BMP-6 have been widely used to block hepcidin production in preclinical and clinical models of anemia in chronic diseases, such as chronic kidney disease, which also exhibit a potential role in reducing the need for EPO." (PMID 37208766, 2023). "The mechanism underlying the deleterious effects observed in cancer patients receiving EPO-stimulating agents to treat anemia is not well understood." (PMID 37543610, 2023). "Afterward, we compared and evaluated the relationship between serum levels of sFas, EPO, and inflammatory markers with anemia over a long period in patients with NDD-CKD." (PMID 37390095, 2023). "There are several factors involved in the prescription of EPO and IV iron and in anemia assessment that are beyond the scope and require further investigation." (PMID 37395543, 2023). "That notwithstanding, evidence suggests a protective role of cigarette smoking against anaemia due to erythropoietin-stimulating influence of smoking-induced increase in carbon monoxide." (PMID 37700371, 2023). "As renal function declines, the kidneys are unable to synthesize adequate levels of erythropoietin which can lead to a progressively more severe anemia." (PMID 37287918, 2023). "Parathyroidectomy in uremic patients has improved the hematocrit levels due to an increase in serum concentration of immunoreactive erythropoietin which is an indirect piece of evidence of the correlation of PTH with anemia in ESRD patients." (PMID 36815007, 2023). "This study ascertained the prevalence of anti-EPO antibody production and evaluated the antibodies’ relationship with Plasmodium falciparum malaria and malaria-related anaemia in pregnancy." (PMID 36989322, 2023). "It should be noted that 16% of patients at an advanced stage were being treated with recombinant erythropoietin (EPO) to prevent anemia." (PMID 37948452, 2023). "Hemolysis stimulates compensatory RBC production by boosting erythropoietin levels; however, this response is often insufficient to restore normal hemoglobin blood levels, resulting in anemia." (PMID 37229037, 2023). "Treatment of anemia in patients with chronic kidney disease (CKD) with recombinant human erythropoietin (rHuEPO) can be disrupted by a severe complication, anti-rHuEPO-induced pure red cell aplasia (PRCA)." (PMID 38123661, 2023). "CKD can contribute to the development of anemia through decreased erythropoietin synthesis and increased hepcidin levels, leading to iron sequestrations and functional ID, including in cancer patients." (PMID 37623041, 2023).
anemia (continued). "Treatment of anemia due to chronic kidney disease was the most frequent indication of erythropoietin." (PMID 38029231, 2023). "Instead, Jehovah’s Witnesses received erythropoietin postoperatively in case of unacceptable anemia." (PMID 37568512, 2023). "EPO is known to regulate the formation of red blood cells by stimulating bone marrow and is widely used for the clinical treatment of anemia." (PMID 37511089, 2023). "Overall, we anticipate more applications for roxadustat in anemia with inflammation, EPO-resistant anemia, and post-transplant anemia." (PMID 36724056, 2023). "Indications for intravenous iron therapy include inadequate therapeutic response to oral iron therapy, anemia requiring rapid normalization, or simultaneous use of erythropoiesis stimulating proteins (e.g., recombinant human erythropoietin [rhEPO], NESP)." (PMID 37435001, 2023). "Anemia of CKD results from a combination of relatively decreased erythropoietin production and the effects of inflammation on iron and erythropoiesis." (PMID 35905974, 2023). "Despite its remarkable safety profile and wide use in the treatment of anemia, EPO’s potent erythropoietic properties limit its development as a CNS drug." (PMID 37511274, 2023). "Therefore, it seems that probably an indirect lowering of FGF23 levels through correction of iron deficiency, anemia, and hyperphosphatemia by iron-based phosphate binders and induction of more physiological EPO production might have a better effect than direct blocking of FGF23 signaling." (PMID 36831276, 2023). "Perioperative hemorrhage and blunted erythropoiesis secondary to decreased iron availability, with concomitant normal or near-normal erythropoietin levels, have been reported as the two major etiologies of perioperative anemia." (PMID 37464433, 2023). "Elevated erythropoietin levels due to sustanined anemia in β-thal stimulate the release of erythroferrone through erythroblasts." (PMID 38293657, 2023). "Testing EPO for screening bone marrow disease can still be a financially reasonable choice for many patients with anemia of unclear etiology." (PMID 37741889, 2023). "Decreased EPO production is one of the reasons for the high frequency of anemia in diabetic patients." (PMID 37378104, 2023). "Expression of Rpp30 is the least affected by experimental conditions of oxygen induced retinopathy, phlebotomy induced anemia and erythropoietin administration at both timepoints of P14.5 and P20." (PMID 37098032, 2023). "Anemia in patients with CKD, known as “renal anemia,” is caused by erythropoietin (EPO) deficiency, and current treatment strategies focus on this condition." (PMID 37605118, 2023). "Anemia is less common but still described in approximately 30–40% of cases, presumably as a consequence of the decreased production of erythropoietin." (PMID 38169885, 2023). "Our results demonstrate that NHD13 mice exhibits anemia, increased serum erythropoietin (EPO), expanded erythropoiesis in the bone marrow and spleen, and parenchymal iron overload, consistent with a low-risk MDS phenotype in patients." (PMID 38153418, 2023). "Appropriate management of anemia in patients with hemodialysis (HD) involves the administration of iron supplementation and erythropoietin-stimulating agents (ESAs), in addition to monitoring the response." (PMID 37391687, 2023). "In fact, a randomized control trial studying 74 patients with preoperative anemia undergoing valvular heart surgery demonstrated that the administration of a single intravenous dose of EPO and iron significantly reduces the need for perioperative transfusions." (PMID 37624779, 2023). "This would facilitate a direct comparison of EPO response between two groups with similar anemia severity but different age and disease status." (PMID 37240288, 2023).
anemia (continued). "Although only a symptomatic treatment for anemia, the benefit for surgical patients is well known, and administration of EPO is recommended by the 2017 EACTS guidelines especially in the preoperative setting." (PMID 37568512, 2023). "Despite anemia driving the increased secretion of erythropoietin, animal studies have shown reduced erythropoietin levels associated with protein depletion suggesting that this can also be seen in patients with EB." (PMID 36823529, 2023). "During erythropoiesis, EPO is required during the process, which is also essential for the treatment of anemia." (PMID 38328786, 2023). "Anemia of chronic disease is normocytic normochromic anemia occurring in chronic inflammatory diseases such as rheumatoid arthritis, cancer, and chronic kidney disease, most likely due to EPO resistance leading to elevated EPO levels in these patients." (PMID 37065412, 2023). "Recombinant human erythropoietin (rHuEPO) has revolutionized anemia management, as it reduces the need for red blood cell (RBC) transfusions and improves anemia-related symptoms and quality of life." (PMID 36839666, 2023). "Non-hemodynamic homeostatic adaptations counter the effect of anemia, increasing erythropoietin (EPO) (stimulating RBC production) and 2,3 DPG (right-shifting the ODC, aiding HbO2 offloading) and altering the intra-erythrocytic milieu (i.e., affecting pH)." (PMID 38235386, 2023). "Further studies should be conducted to elucidate the significance and effect of anti-EPO antibodies on the health of pregnant women, especially those presenting with P. falciparum malaria and anaemia." (PMID 36989322, 2023). "The HALP score's individual components are especially relevant to CKD patients due to the prevalence of anemia (i.e., low hemoglobin levels) secondary to decreased kidney erythropoietin (EPO) production." (PMID 37284646, 2023). "Recently, it has been shown that erythropoietin (EPO), employed for the treatment of anemia, also demonstrates therapeutic effects in respiratory disorders such as ALI, as it suppresses the NLRP3 inflammasome." (PMID 38068879, 2023). "In patients diagnosed with CKD, anemia is induced by disturbed renal erythropoietin (EPO) production, which is responsible for erythropoiesis." (PMID 37629516, 2023). "Anaemia improved with treatment with cidofovir, intravenous immunoglobulin, reduction in immunosuppression and erythropoietin stimulating agent." (PMID 37723433, 2023). "The anaemia was treated with blood transfusion, four doses of intravenous immunoglobulin, and a third course of cidofovir, and continuation of erythropoietin stimulating agent." (PMID 37723433, 2023). "In spite of the association between anemia and COPD, the role of erythropoietin (EPO) in this content is still unclear." (PMID 37117600, 2023). "In this process, erythropoietin (EPO)-producing fibroblasts also convert to myofibroblasts, so that these cells reduce EPO production, resulting in anemia." (PMID 36725898, 2023). "Due to a decrease in erythropoietin secretion levels resulting from the reduction of kidney function, anemia is common in CKD patients, and the prevalence of anemia is strongly associated with a declining estimated glomerular filtration rate." (PMID 37190900, 2023). "Another instance included in functional ID is the imbalance between iron supply and demand when erythropoiesis is accelerated because of elevated erythropoietin (EPO) levels (endogenous response to anemia) or treatment with erythropoiesis-stimulating agents." (PMID 36673114, 2023). "Chronic diseases are known to trigger inflammatory processes that can lead to anemia by reducing the lifespan of red blood cells and impairing the response of red blood cell progenitors to erythropoietin." (PMID 37679719, 2023). "Our study aimed to assess the role of intravenous iron and erythropoietin therapy for the rapid correction of anemia following orthopedic surgery." (PMID 37464433, 2023).